GSS (glutathione synthetase)
Description:
Catalyzes the production of glutathione from gamma-glutamylcysteine and glycine in an ATP-dependent manner. Glutathione (gamma-glutamylcysteinylglycine, GSH) is the most abundant intracellular thiol in living aerobic cells and is required for numerous processes including the protection of cells against oxidative damage, amino acid transport, the detoxification of foreign compounds, the maintenance of protein sulfhydryl groups in a reduced state and acts as a cofactor for a number of enzymes. Participates in ophthalmate biosynthesis in hepatocytes (By similarity).
Synonyms: CNSHA6; GSHS; HEL-S-64p; HEL-S-88n
Tractability: Small molecule: a structure with a bound ligand is known; it has a high-quality binding pocket. PROTAC: ubiquitination databases record sites on it; its protein half-life has been measured.
Target class: Enzyme; Ligase
Gene: Protein-coding gene on chromosome 20 (34,928,432 to 34,956,027, reverse strand). Ensembl gene ENSG00000100983.
Subcellular location (Human Protein Atlas): Nucleoplasm
Pathways (Reactome):
Disease: Defective GSS causes GSS deficiency
Metabolism: Glutathione synthesis and recycling
Gene Ontology:
Molecular function: ATP binding; glutathione binding; glutathione synthase activity; identical protein binding; magnesium ion binding; protein binding; protein homodimerization activity; ligase activity
Biological process: glutathione biosynthetic process; amino acid metabolic process; nervous system development; response to oxidative stress
Cellular component: extracellular exosome; nucleoplasm; cytosol
Genetic constraint (gnomAD): Loss-of-function variants: 31 observed, 51.1 expected, observed/expected ratio (o/e) 0.61, 90% interval 0.46 to 0.82. The upper end of that interval is the gene's LOEUF score, 0.82, which puts it in group 3 of 6, group 1 being the genes least tolerant of losing a copy. Missense variants: 431 observed, 548.44 expected, observed/expected ratio (o/e) 0.79, 90% interval 0.73 to 0.85. Synonymous variants: 206 observed, 222.85 expected, observed/expected ratio (o/e) 0.92, 90% interval 0.82 to 1.04.
Gene-disease validity (ClinGen):
ClinGen rates the evidence that GSS causes each of these diseases.
inherited glutathione synthetase deficiency (autosomal recessive): Definitive.
Homologues: Orthologues: chimpanzee GSS (99% identical), macaque GSS (98% identical), pig GSS (93% identical), dog GSS (92% identical), guinea pig GSS (91% identical), rabbit GSS (90% identical), mouse Gss (89% identical), rat Gss (88% identical), tropical clawed frog gss (65% identical), zebrafish gss (62% identical), Drosophila melanogaster Gss1 (41% identical), Drosophila melanogaster Gss2 (41% identical), and 1 more.
Diseases named in the same sentence as GSS in open-access papers:
GSS is named in the same sentence as 72 diseases in open-access papers, as found by Europe PMC text mining. Sharing a sentence is not in itself a finding about the gene and the disease. The quoted sentences say what the papers report.
Glutathione synthetase deficiency (7 papers, 2007 to 2025). "GSS (Glutathione synthetase) is related to glutathione synthetase deficiency, which go along with central nervous damage." (PMID 39026379, 2024). "Glutathione synthetase deficiency (GSSD) is an autosomal-recessive metabolic disorder caused by glutathione synthetase (GSS) gene mutations." (PMID 37576147, 2023). "An example of an IEM pathology being caused by loss of enzyme product would be glutathione synthetase deficiency, in which the enzyme glutathione synthetase (GSS), required to produce the antioxidant glutathione, is impaired." (PMID 35736461, 2022). "Since the human genome contains only one glutathione synthetase gene, the various clinical forms of glutathione synthetase deficiency reflect different mutations or epigenetic modifications in the glutathione synthetase gene." (PMID 17397529, 2007). "Mutations in GSS cause glutathione synthetase deficiency and result in various metabolic diseases." (PMID 36276334, 2022). "Although GCLC-KO mice do not model glutathione synthetase deficiency per se—which is caused by mutations in the GSS gene and presents with severe systemic glutathione depletion and neurological symptoms—they reproduce key features of brain redox imbalance." (PMID 40671004, 2025).
breast carcinoma (6 papers, 2012 to 2025). "Mouse mammary tumor stem cells overexpress glutamate-cysteine ligase and glutathione synthetase, enzymes involved in the synthesis of the principal cellular antioxidant glutathione." (PMID 26808816, 2016). "In general, more aggressive breast cancers (MDA-MB-231, SUM159PT, BCCL2, BCCL3) had lower levels of TMX1 and SOD1 relative to the luminal MCF-7 cells, and showed up-regulated expression of TMX3, Foxo1, GSS and SOD2." (PMID 22479642, 2012).
colon cancer (5 papers, 2017 to 2025). "Moreover, the protein expression of GSS, an enzyme involved in de novo glutathione synthesis, was markedly elevated in the treated colon cancer cells." (PMID 40649986, 2025). "Furthermore, the protein expression of glutathione synthetase (GSS), a key enzyme in glutathione biosynthesis, was significantly increased in the treated colon cancer cells compared to the controls, considering the quantified fluorescence on the obtained micrographs." (PMID 40649986, 2025). "Other studies reported that luteolin inhibits methylation of the Nrf2 promoter region in colon cancer HT-29 and SNU-407 cells, thereby increasing apoptosis-related proteins and antioxidant enzymes such as GCLC, glutathione synthetase (GSS), catalase, and HO-1." (PMID 34067204, 2021).
type 2 diabetes (4 papers, 2021 to 2023). "The present study was the first to assess the contribution of two genes encoding glutathione synthetase and gamma-glutamyl transferase 7 to the development of type 2 diabetes mellitus." (PMID 34575035, 2021). "Our recent study discovered that polymorphisms in genes encoding glutathione metabolizing enzymes, such as glutathione synthase (GSS) and gamma-glutamyltransferase 7 (GGT7), are associated with susceptibility to type 2 diabetes." (PMID 37569434, 2023). "The pancreatic expression of genes correlated with the T2D-associated SNPs of GSS and GGT7 has attracted the most attention since the organ is primarily involved in the development of type 2 diabetes." (PMID 34575035, 2021). "The present study investigated whether type 2 diabetes (T2D) is associated with polymorphisms of genes encoding glutathione-metabolizing enzymes such as glutathione synthetase (GSS) and gamma-glutamyl transferase 7 (GGT7)." (PMID 34575035, 2021). "Furthermore, reduced expression of GSH synthesizing enzymes, such as GCLC, GSS, and GGT, is associated with lower GSH levels in people with type 2 diabetes mellitus (T2DM)." (PMID 37239011, 2023).
5-Oxoprolinuria (3 papers, 2007 to 2023). "Chronically high levels of L-pyroglutamic acid are associated with several inborn errors of metabolism, like 5-Oxoprolinuria, 5-oxoprolinase deficiency, Glutathione Synthetase Deficiency, Hakinsinuria, and Propionic acidemia." (PMID 37627634, 2023). "5-Oxoprolinuria results most often from an enzymatic deficiency at the level of glutathione synthetase (step 1) or 5-oxoprolinase (step 4)." (PMID 27339215, 2016). "The diagnosis usually involves the following: clinical findings, the finding of 5-oxoprolinuria, low levels of glutathione, low activity of glutathione synthetase, and mutation analysis of the glutathione synthetase gene." (PMID 17397529, 2007).
liver cancer (3 papers, 2015 to 2024). An epithelial or non-epithelial malignant neoplasm that arises from the liver. "Furthermore, the effects of RRM2 on elevating GSH were abolished when GSS was knocked out by CRISPR-Cas9 technology in both HepG2 and SMMC-7721 cells, demonstrating that GSS is a prerequisite for RRM2 to upregulate GSH in liver cancer cells." (PMID 33372599, 2020).
ovarian carcinoma (3 papers, 2011 to 2025). A malignant neoplasm originating from the surface ovarian epithelium. "In the combined TCGA and GTEx data, GSS mRNA levels were significantly higher in cervical cancer and ovarian cancer tissues compared to normal tissues." (PMID 41431124, 2025). "We performed quantitative RT-PCR todetermine the gene expression level of glutamate-cysteine ligase (GCLM) andglutathione synthase (GSS), in the Bmi-1 siRNA transfected ovarian cancer celllines." (PMID 21445297, 2011). "Finally, we explored whether factors such as ATF4, GPX4, GSS, KEAP1, NFE2 like BZIP transcription factor 2 (NEF2L2), SLC7A11, SQSTM1, ATG3, ATG4D, and ATG5 have potential as non-invasive diagnostic markers for ovarian cancer." (PMID 37215446, 2023). "The results of cDNA expression profile analysis indicated that six genes, including GPX4, GSS, KEAP1, SQSTM1, SLC7A11, ATG3, and ATG5, were highly expressed in tumor tissues from patients with ovarian cancer." (PMID 37215446, 2023). "The results of the data analysis indicated that the contents of ATF4, GPX4, GSS, KEAP1, and ATG3 in the peripheral blood exosomes of patients with ovarian cancer were significantly higher than those of the healthy controls." (PMID 37215446, 2023). "Kaplan-Meier plot analysis indicated that the expression levels of GSS, KEAP1, ATG3, and ATG4D correlated significantly and negatively with the survival of patients with ovarian cancer." (PMID 37215446, 2023). "In addition, we performed exosome database screening and found that the levels of ATF4, GPX4, GSS, KEAP1, and ATG3 in the peripheral blood exosomes of patients with ovarian cancer were significantly higher than those from the healthy controls." (PMID 37215446, 2023). "The results of multiple gene correlation analyses indicated that there was a significant linear relationship (positive correlation) between the expression of ATF4 in ovarian cancer tissue and the expression levels of GPX4, GSS, KEAP1, NFE2L2, SLC7A11, ATG3, ATG4D, and ATG5." (PMID 37215446, 2023).
colorectal cancer (2 papers, 2017 to 2025). A primary or metastatic malignant neoplasm that affects the colon or rectum. "Previous studies have demonstrated that in colorectal cancer, GSS overexpression significantly enhances metabolic flux from cysteine to GSH, thereby promoting tumour growth." (PMID 41431124, 2025).
COVID-19 (2 papers, 2022 to 2025). A disease caused by infection with severe acute respiratory syndrome coronavirus 2. "Increased DNA oxidative damage and significantly decreased activity of antioxidant enzymes CAT and glutathione synthetase (GSS) were found in placentas of asymptomatic and symptomatic pregnant COVID-19 female patients compared to healthy controls." (PMID 36009328, 2022).
glioblastoma (2 papers, 2023 to 2025). The most malignant astrocytic tumor (WHO grade IV). "Furthermore, high IL-11Rα expression also correlated with increased expression of GLUD1 and GSS, two key enzymes involved in glutaminolysis in both our glioblastoma cell lines and patient tumor tissue." (PMID 36834778, 2023). "For glioblastoma (GBM), a blood-brain barrier-penetrating delivery system was developed using Angiopep-2/TAT peptide-modified extracellular vesicles (EVs) to transport Cas9/sgRNA complexes targeting glutathione synthetase (GSS)." (PMID 40709182, 2025). "Furthermore, IL-11Rα expression in glioblastoma patient samples correlated with enhanced gene expression of the glutaminolysis pathway genes GLUD1, GSS and c-Myc." (PMID 36834778, 2023). "Indeed, glioblastoma patient tumor tissue with low IL-11Rα gene expression also displayed low levels of GLUD1 and GSS, while patient tumor tissue containing high IL-11Rα gene expression also contained significantly higher levels of GLUD1 and GSS gene expression." (PMID 36834778, 2023).
glioma (2 papers, 2021 to 2023). A benign or malignant brain and spinal cord tumor that arises from glial cells (astrocytes, oligodendrocytes, ependymal cells). "Especially, in silico analysis of glioma tissues of the multidimensional data set from TCGA revealed that CD147 are broadly positive associated with Nrf2 target genes regulating redox homeostasis, including NQO-1, HO-1, GSTK-1, and GSS, which further confirmed the CD147 regulation of Nrf2." (PMID 34421346, 2021). "In our study, GSS (glutathione synthetase) and GCLC had similar functions in synthesising glutathione, but they play opposite roles in promoting and inhibiting glioma progression." (PMID 38057821, 2023).
kidney damage (2 papers, 2023 to 2025). "In addition, these 106 potential classifiers/biomarkers between TCMR vs. STA are associated with kidney damage (e.g., ATP1B1, CST3, FAH, GSS, HPX and LYZ), tubule injury (e.g., CRYM, GSS, HAGH, HPX and LYZ) and kidney inflammation (e.g., DCN)." (PMID 36814924, 2023).
lymphoma (2 papers, 2016 to 2021). A malignant (clonal) proliferation of B- lymphocytes or T- lymphocytes which involves the lymph nodes, bone marrow and/or extranodal sites. "The main finding of this study is that by reproducing in vitro a condition of in vivo hyperCHO, lymphoma lymphoblastic cells overexpressed genes for antioxidant proteins (SOD1, SOD2, CCS, GSR, GSS and CAT) with the only exception of GRX2." (PMID 26754536, 2016).
prion disease (2 papers, 2017 to 2021). A transmissible disease that is caused by a protein that is able to induce abnormal folding of normal cellular proteins, leading to characteristic spongiform brain changes, which are associated with neuronal loss without an inflammatory response. "From 2001 to 2020, a total of 305 cases of prion diseases were definitively confirmed, of which 256 cases were sCJD, 41 cases were gCJD, and 8 cases were GSS, which corresponds to a total prevalence of approximately 15.25 cases per year." (PMID 34679519, 2021). "As for SERPINA3, GFAP was up-regulated in all prion diseases, with the highest value observed in gCJD patients (FC = 5.2) and iCJD (FC = 5), sCJD (FC = 3), GSS (FC = 2.9, not significant) vCJD (FC = 2.8) and FFI (FC = 2.2)." (PMID 29142239, 2017). "SERPINA3 was found to be strongly up-regulated in all prion diseases: sCJD (FC = 40.3), vCJD (FC = 38.8), FFI (FC = 52.7), gCJD (FC = 39.1) and GSS (FC = 12.17, not significant) cases." (PMID 29142239, 2017).
renal cell carcinoma (2 papers, 2011 to 2024). "For example, RRM2 activated the AKT pathway by directly binding to and stabilizing ANXA1 in renal cell carcinoma, and in HCC cells it sustained intracellular glutathione (GSH) by protecting glutathione synthetase (GSS) from degradation." (PMID 39243109, 2024).
thyroid cancer (2 papers, 2021 to 2024). "According to data retrieved from the Cancer Genome Atlas (TCGA) database, the glutathione enzyme (GSS) expression levels in thyroid cancer cells were significantly higher than that in normal thyroid cells." (PMID 38977966, 2024). "Univariate cox regression analysis demonstrated that DPP4 [hazard ratio (HR): 0.756, 95% confidence interval (CI): 0.623–0.918, p = 0.004], GPX4 (HR: 0.381, 95% CI: 0.147–0.990, p = 0.048) and GSS (HR: 0.361, 95% CI: 0.139–0.935, p = 0.036) were protective factors for thyroid cancer prognosis." (PMID 33928101, 2021). "Our data suggested that AKR1C1 (p < 0.0001), DPP4 (p < 0.0001), GPX4 (p = 0.0001), GSS (p < 0.0001), HMGCR (p < 0.0001), TFRC (p < 0.0001), SQLE (p = 0.0004), and PGD (p = 0.0005) were all significantly highly expressed in thyroid cancer tissues compared to normal tissues." (PMID 33928101, 2021).
asthenozoospermia (1 paper, 2024). "Histone H4, cathepsin L, glutathione synthetase, and ENO1 emerged as potential biomarkers for asthenozoospermia." (PMID 38605082, 2024). "Furthermore, proteins histone H4, cathepsin L, glutathione synthetase and ENO1 are proposed as potential biomarkers of autophagy and vitality in asthenozoospermia sperm." (PMID 38605082, 2024).
cervical cancer (1 paper, 2025). A primary or metastatic malignant neoplasm involving the cervix. "This study sought to develop cuproptosis‐based diagnostic and prognostic models for cervical cancer using integrated multi‐omics and machine learning, and to functionally characterise the core gene glutathione synthetase (GSS) to identify potential biomarkers and therapeutic targets." (PMID 41431124, 2025). "More importantly, IHC experiments performed on five pairs of clinical cervical cancer and matched adjacent normal tissues confirmed the specific overexpression of GSS protein in tumour tissues." (PMID 41431124, 2025).
Cirrhosis (1 paper, 2021). A chronic disorder of the liver in which liver tissue becomes scarred and is partially replaced by regenerative nodules and fibrotic tissue resulting in loss of liver function. "Progression of chronic liver diseases leads to the development of cirrhosis, when zonal distribution of hepatocytes is completely lost and glutathione synthetase synthesis practically stops (disruption of the glutathione cycle)." (PMID 34513073, 2021).
eosinophilic esophagitis (1 paper, 2023). Eosinophilic esophagitis (EoE) is a chronic, allergic disease of the esophagus characterized clinically by symptoms of esophageal dysfunction (including vomiting, dysphagia, feeding disorders, food impaction and abdominal pain) which persist after treatment with proton pump inhibitors (PPIs). "Independently, L-pyroglutamic acid is a biomarker in Eosinophilic Esophagitis (in urine) and Glutathione Synthetase Deficiency (in urine and blood)." (PMID 37627634, 2023).
gastric adenocarcinoma (1 paper, 2024). "As assessed by IHC of patient tumor tissues, the cytoplasmic expression of both GSS and GPX4 was detected on tumor cells of gastric adenocarcinoma and PDAC, as well as in lymph nodal metastatic sites of PDAC." (PMID 39666242, 2024).
giardiasis (1 paper, 2023). An infection of the small intestine caused by the flagellated protozoan giardia lamblia. "Furthermore, glutathione synthetase expression was downregulated during giardiasis, with respect to the other infections, especially in the jejunum, ileum, and colon." (PMID 36675151, 2023).
gout (1 paper, 2024). A condition characterized by painful swelling of the joints, which is caused by deposition of urate crystals. "In conclusion, our study analyzed the expression changes of ferroptosis-related proteins ACSL4, VDAC2, GPX4, and GSS in the urinary exosomes of gout patients." (PMID 39606034, 2024).
hepatocellular carcinoma (1 paper, 2024). A malignant tumor that arises from hepatocytes. "The results of Western Blot showed that curcumin decreased the expression of ferroptosis-related proteins SLC7A11, GSS, GPX4, and FTH1, as well as increased the expression levels of PTGS2 and ACSL4 in hepatocellular carcinoma tissues." (PMID 39311951, 2024).
HIV-1 infection (1 paper, 2016). The type species of lentivirus and the etiologic agent of acquired immunodeficiency syndrome (AIDS). "Decreased levels of GSH in individuals with HIV-1 infection were accompanied by diminished levels of enzymes, such as GCLC and GSS in the red blood cells." (PMID 27335804, 2016).
ischemia (1 paper, 2023). A hypoperfusion of the BLOOD through an organ or tissue caused by a PATHOLOGIC CONSTRICTION or obstruction of its BLOOD VESSELS, or an absence of BLOOD CIRCULATION. "In addition, UA also revealed antioxidant activity, observed as an increase in superoxide dismutase (SOD) and glutathione synthetase (GSH) activity in hippocampal cells, which may support its anti-inflammatory activity against ischemia." (PMID 37109575, 2023).
ischemia reperfusion injury (1 paper, 2022). Adverse functional, metabolic, or structural changes in ischemic tissues resulting from the restoration of blood flow to the tissue (reperfusion), including swelling; hemorrhage; necrosis; and damage from free radicals. "Injection of 5-MTHF significantly increased the expression of mRNA and protein levels of glutamate-cysteine ligase (Gclc) in the kidneys of rats with ischemia-reperfusion injury; however, such treatment did not affect the expression of Gclm and glutathione synthetase." (PMID 35739943, 2022).